SOX2 (SRY-box transcription factor 2)
Diseases named in the same sentence as SOX2 in open-access papers (continued):
Sharing a sentence is not in itself a finding about the gene and the disease.
tumor (continued). "Differences in the spatial expression pattern between SOX2 and SOX9 at protein levels were assessed in two distinct areas of the tumor tissue: the invasion front and the tumor core." (PMID 38275880, 2024). "To investigate expression of N1-ICD and SOX2 within the same tumor and/or cell, we performed immunofluorescence co-staining for N1-ICD and SOX2 in all four TNBC xenograft models." (PMID 39478150, 2024). "In summary, our data indicates that DUSP1 and SOX2 have opposite functions in SG-SCC, being DUSP1 necessary for tumor growth and SOX2 dispensable showing a tumor suppressor function." (PMID 38951654, 2024). "Tumor sphere (TS) formation is often used to assess CSC-like characteristics, and specifically, it has been reported that SOX2 overexpression enhances TS formation in H358 LUAD cells." (PMID 38334608, 2024). "Our findings identified a new molecular relationship between SOX2 and NOTCH1 in the context of drug resistance and tumor cell plasticity in TNBC." (PMID 39478150, 2024). "Studies have demonstrated that KMT2D modulates SOX2 expression in NSCLC through a PI3K-dependent manner, significantly impacting tumor growth." (PMID 39544292, 2024). "The tumor volume and weight of mice harboring PSMD7-silenced cells exhibited a remarkable reduction, whereas simultaneous SOX2 overexpression completely abrogated the antitumour effects of PSMD7 knockdown." (PMID 38494478, 2024). "Napabucasin downregulates stemness-related genes Nanog, SOX2, Klf4, and Oct4 CD90 and EpCAM mRNA expression levels both in tumor cells and tumor tissues." (PMID 37570646, 2023). "After 5 weeks, the tumor organoids (referred to as tumoroids), shown to contain corticotrope (ACTH+), stem/progenitor (SOX2+) and intermediate (PITX1+, TBX19+) cell populations, were moved to spinner flasks, which further increased ACTH production." (PMID 37614709, 2023). "The transcription factors SOX2 and OCT4 participate in embryogenesis and stem cell maintenance and contribute to CSC formation, tumor growth, and metastasis upon inappropriate cytoplasmic or nuclear localization." (PMID 38201518, 2023). "Among these genes, the known stem cell marker SOX2 is the determining oncogenic switch in promoting LUSC from different cells of origin, suggesting distinct tumor progression trajectories for these two NSCLC subtypes." (PMID 37046851, 2023). "Regarding stem-cell characteristics, NEK8 knockdown decreased the tumour sphere formation, aldehyde dehydrogenase activity, and stem-cell marker expression, including that of CD44, Sox2, Oct4a, and Nanog." (PMID 37100815, 2023). "This response triggers several functions, including the regulation of stemness through transcription factors (such as SOX2, KLF4, NANOG, MYC, and OCT4) that promote cancer cell survival and sometimes correlate with poor prognosis and tumor progression." (PMID 37371030, 2023). "Upregulation of SOX2 in chemotherapy-resistant GBM tissues and cells facilitates the malignant phenotype by regulating tumor-initiation and drug-resistant cell survival." (PMID 37058447, 2023). "The expression of SOX2 is upregulated in NSCLC tissues with distant metastasis compared to tumors in situ, and prior studies have demonstrated that SOX2 is related to tumor cell stemness and promotes tumor progression." (PMID 38057344, 2023). "In fact, SRR2 deletion was shown to down-regulate SOX2 and reduce cell proliferation in GBM cells, highlighting enhancer specificity to different tumor types." (PMID 37738673, 2023). "qPCR analysis showed that the expression of CD133, CD44, and OCT4 and SOX2, EpCAM, and LGR5 in CSC sphere cells enriched after the addition of micro serum was higher than that in tumor cell spheres enriched in serum-free medium." (PMID 37639070, 2023). "Western blot analysis of tumor tissues validated that the protein expression of NANOG and SOX2 was significantly lower in the IL20RB knockdown group than in the control group." (PMID 38098005, 2023).
tumor (continued). "Our data demonstrate the implication of SOX2 in promoting DNA damage and genome instability by sustaining inflammation via FOSL2/IL6, resulting in tumor aggressiveness." (PMID 36932385, 2023). "Under hypoxic conditions, CD44-ICD binds to HIF-2α and activates HIF-2α expression, which further activates HIF-2α target genes, including cyclin D1, Nanog, Oct4, Sox2, and OPN, resulting in the promotion of tumor proliferation and stemness of GSCs." (PMID 37835592, 2023). "In addition, a tumor-burden mice model by cell transplantation further demonstrated the promotion of tumor growth by pMX-CCAT2 in vivo, which was associated with increased levels of cell proliferation factors (Ki67 and CCND1) and cell stemness genes (h-TERT, NANOG, SOX2, KLF4 and OCT4)." (PMID 36672487, 2023). "Downregulation of PrPC caused by melatonin can prevent the expression of the stem cell markers Oct4, Nanog, Sox2 and ALDH1A1, which inhibits tumour development, proliferation and tumour-mediated angiogenesis by affecting ISCs." (PMID 37101229, 2023). "The increase in tumor incidence correlated with high levels of HIF-1α, maintenance of high expression of pluripotency genes Oct4, Sox2 and Nanog, elevated activity of the Nodal signal pathway, and suppression of germ cell mitotic arrest." (PMID 37180974, 2023). "SOX-2 labelling was present predominantly in the nucleus, while NANOG and OCT4 were found in the cell nucleus and diffusely in the cytoplasm of tumour parenchymal cells." (PMID 36655039, 2023). "IHC staining of tumor sections revealed that the levels of ALDH1, CD44, CD133, SOX2, Notch1, EZH2 and CCND1 were downregulated in CDK5RAP2-knockdown tumors." (PMID 36774351, 2023). "Patients with a poor prognosis had tumours with higher levels of the pluripotent markers OCT4 and SOX2, in addition to the polycomb complex protein Bmi-1." (PMID 36968194, 2023). "In nude mice, the IMPDH1 inhibitory drug MMF inhibited tumor growth and reduced the expression of tumor stem cell characteristic markers CD133 and SOX2." (PMID 36711025, 2023). "And the key roles of SOX2 and SOX9 in the regulation of cancer stemness and tumor metastasis have been well-documented in previous studies." (PMID 36902193, 2023). "IHC of tumor tissue sections showed that the protein levels of NANOG and SOX2 in the IL20RB knockdown group was significantly lower than those in the control group." (PMID 38098005, 2023). "Additional characterization of tumor markers for BLT-derived GBM8 and GBM18 was performed, including SOX2, CD31, and Ki67." (PMID 38274817, 2023). "Following A3C knockdown, the expression of tumor stemness markers (CD133, SOX2), exhibiting a strong correlation with A3C expression, was subsequently diminished compared to the control." (PMID 37809064, 2023). "As a stem cell transcription factor, Sox2 can affect the proliferation, metastasis, invasion, apoptosis, drug resistance, and TSC properties of various tumor cells." (PMID 36869031, 2023). "A parallel analysis was performed in ESCC, which identified a number of tumor-specific factors, including RUNX1/3, SOX2/4, and CEBPA/B." (PMID 37620896, 2023). "FUT9-mediated hyperfucosylation also triggered Sox2, ALDH, and CD44 expression and tumor sphere formation." (PMID 37298124, 2023). "Key properties of these GBM stem-like cells include the expression of genes that promote the stem-like state (e.g., SOX2, OCT4) and facilitate tumor proliferation and resistance to radiation and chemotherapy." (PMID 37395278, 2023).
tumor (continued). "Hypoxia promotes a stem-like phenotype in tumor cells through the activation of genes such as OCT4, SOX2, c-MYC, CD44, CD133, WNT, Notch, and NANOG, leading to dedifferentiated and undifferentiated tumor phenotypes associated with more aggressive biology." (PMID 38132455, 2023). "Shikonin (SHK), for example, induced apoptosis and inhibited migration, invasion, and xenograft tumor growth, as well as the expression of CSC-related markers (ALDH1, OCT4, SOX2, and NANOG) in OC." (PMID 37445860, 2023). "Tumor samples from corresponding patients were collected and IHC was used to evaluate the quantity and localization of the GBM tumor cell marker SOX2 and GAL1 (Table EV2)." (PMID 37791581, 2023). "In confirmation, immunoblotting revealed a dose dependent reduction in expression of CSC makers (Sox2, Oct4, Nanog and ALDH1A1) in the ART-treated tumors compared to the untreated tumor." (PMID 38144525, 2023). "Our results reveal that the GSCAR/miR-6760-5p/SRSF1 axis is important for tumor growth, while the GSCAR/DHX9-IGF2BP2/Sox2 feedback loop is critical for GSC maintenance and TMZ resistance." (PMID 37063420, 2023). "Cell populations expressing or not CD44-positive cells were sorted out by flow cytometry and detected by Western Blot and RT-qPCR for the tumor stemness markers OCT4 and SOX2." (PMID 37980488, 2023). "We identified that CDK1 activates STAT3 to regulate tumor sphere formation and the expression of stemness-related genes CD44 and SOX2, as well as both CDK1 and STAT3, which are negatively correlated with the prognosis of PDAC patients." (PMID 37743465, 2023). "Here, we found that BMI1, CD44, SOX2, OCT4, UBE2C, CXCR4 CSCs marker genes are significantly upregulated, while IGF1-R, KLF4, ALDH1A1, CD133, FAM3C are downregulated in the tumor core vs healthy mucosa of 24 patients with OSCC." (PMID 38096163, 2023). "The potential of circulating tumor cells as non-invasive biomarkers for assessing NR5A2 and SOX2 expression should be explored." (PMID 38012687, 2023). "SOX2 bound to the CD39 promoter, regulated the level of eATP in TME, and affected the recruitment of DCs to apoptotic tumor cells and T cell killing effect on GSCs, leading to immune escape." (PMID 35159053, 2022). "SOX2 expression was confirmed as a CSC marker by several authors based on its capacity to induce CSC properties, including stemness, as evidenced by tumor-initiating capacity, sphere formation, selective chemoresistance and promotion of in vivo tumorigenicity." (PMID 35162954, 2022). "Only IL-8 was crucial for self-renewal, tumorsphere formation and tumor initiation capabilities as well as the expression of the stemness markers OCT4, SOX2, and NANOG." (PMID 36118530, 2022). "Taken together, these clinical and molecular data show that TET2 downregulation by SOX2 drives GBM cell stemness and in vivo tumor growth." (PMID 35136034, 2022). "Overall, moderate to strong expression of SOX2 and ALDH1A1 was observed more frequently in tumor buds than in the main tumor body (51.7% vs. 9.2%; 48.3% vs. 20.7%, respectively; both P < 0.001)." (PMID 35860042, 2022). "VEGF-A promoted tumor cell self-renewal through VEGF-A/VEGF-R/STAT3 signaling resulting in activation of Myc, Sox2 and STAT351–53." (PMID 35351947, 2022). "FXOM1 linked closely with the expression levels of stem cell markers (Nanog, Sox2, and OCT4) in various tumor samples, and also in turn potentiated the expression of these stemness-related genes in vitro." (PMID 35945194, 2022). "However, in the last decade, SOX2 has been characterized beyond its role in embryonic stem cells, and evidence has shown that there may be a therapeutic benefit in targeting SOX2 to reduce its probable tumor-initiating capacity in various cancers." (PMID 36551731, 2022). "Sox2 is highly expressed in NSCLC, determines tumor chemoresistance, and contributes to maintaining tumor cell stemness." (PMID 36555420, 2022).
tumor (continued). "On the other hand, tumor-sphere in A549 cells expressed only three genes (ALDH1A1, Oct4, and Sox2), and dinactin significantly reduced the relative expression of only ALDH1A1." (PMID 36551502, 2022). "The expression of TWIST1, CRIPTO1, SOX2, and MSI1 were evaluated in ESCC patients, indicating their role in tumorigenesis and tumor cell aggressiveness." (PMID 36553636, 2022). "Collectively, SOX2 upregulation dampened intrinsic host immune activation of cGAS /STING signalling, and inhibited IR‐induced anti‐tumour immune responses." (PMID 35415876, 2022). "Both Sox2+Nestin+ and CD105+Nestin+ cell populations exist in this area, but CD105+Nestin+ cells were more numerous and locate around angiogenic tumor capillaries." (PMID 36038950, 2022). "The downregulation of SOX2 and SOX3 to influence tumour cell invasion was examined with Transwell invasion assays." (PMID 34953010, 2022). "Intratumoral Fn injection led to an increase of formate levels within tumour interstital fluids (TIFs), accompanied by an increased AHR, CYP1B1, SOX2 and ALDH1A1 (trendwise) gene expression." (PMID 35437333, 2022). "In the present study, NK cell markers were detected in human GBM tissue sections in close proximity of tumor vasculature and cells positive for GSLC markers SOX2 and CD44." (PMID 35538218, 2022). "The downregulation of SOX2 and SOX3 to influence tumour cell migration was evaluated using wound‐healing migration assay." (PMID 34953010, 2022). "Nanog, octamer-binding protein 4 (OCT4), SRY-box 2 (SOX2) and Kruppel-like factor 4 (KLF4) are key participants of tumor stemness." (PMID 35864972, 2022). "Multivariable linear regression was performed to ascertain the possible relation between distance from tumor centroid to SVZ and age, sex, and percentage of positive core cells of SOX2, SOX9, Nestin, and Ki67." (PMID 35795469, 2022). "On the other hand, we observed a reduction in SOX2 mRNA levels, in CHA overexpressing HCT116 cell‐derived tumours, while TCFL5_E8 overexpression tended to increase it." (PMID 34623757, 2022). "Mice implanted with MDA-MB-231 NTC or A2BR knockdown subclones were treated with 10 mg/kg paclitaxel every 5 days for three doses and tumor samples were collected for ChIP followed by qPCR with primers flanking FOXO3 binding site of NANOG, SOX2 and KLF4 genes." (PMID 35401817, 2022). "The Hippo pathway, which is under the transcriptional control of Sox2, was directly related to the same activities, and deactivating Sox2 effectors (e.g., YAP) resulted similarly in a reduction in tumor growth." (PMID 35582537, 2022). "Induction of a proliferative state at distant sites was associated with high levels of the stem-like/progenitor marker, SOX2, and required the upregulation of FMOD, an extracellular matrix component, which modulates tumor–stroma interactions." (PMID 35737114, 2022). "The effect of toyocamycin on p21, ID2, OCT4, SOX2 and NANOG expression was also verified in the tumor sections by immunohistochemistry." (PMID 35078502, 2022). "Despite the very recently discussed role of SOX2 in driving GBM stemness and tumor propagation, we found the dimerization partner of OCT4 to be expressed on a low level." (PMID 36361720, 2022). "Hybrids increase the expression of the stemness factors OCT4, NANOG, SOX2, and LIN28, upregulate CD44 and CD133 as well as promote gastric xenograft tumor growth in vivo." (PMID 35205716, 2022). "Inhibition of PCAT1/SOX2 enhanced IR‐induced cGAS/STING activation and anti‐tumour immune responses." (PMID 35415876, 2022). "The results revealed that SALB reversed chemotherapy resistance to 5-FU and oxaliplatin and inhibited tumor growth by suppressing the expression of stemness markers, such as CD44, CD133, and the transcription factor sox-2 (SOX2)." (PMID 36172536, 2022). "In the present study, we found that AGK enhanced the tumor sphere potential and the expression of stemness genes increased, such as ALDH1, SOX2, OCT4, NANOG, LIN28 and EOC stemness gene CD44." (PMID 35934718, 2022).
tumor (continued). "Western blot detection also found that expression of stemness markers SOX2, OCT-4, Nanog and CD133 was decreased after circ-EPB41 silencing in tumor tissues, suggesting that circ-EPB41 promoted the progression of NSCLC by regulating stemness." (PMID 35725615, 2022). "We showed that the SOX2 reprogramming TF that drives GBM cell stemness and tumor-propagating potential induces miR-10b-5p that targets TET2 that we show inhibits GBM cell stemness and GBM xenograft growth." (PMID 35136034, 2022). "To clarify the existence of GSCs outside the tumor front, we obtained biopsies from GBM patients in the immediate peri-tumor region and mapped the tumor stem-like cells with the markers Sox2, Nestin and CD105." (PMID 36038950, 2022). "Due to the direct interaction between SOX2/NANOG/BMI1/KLF4 in the invasiveness of tumor cells, as well as its biological significance in the progression of ESCC, SOX2 expression can enhance malignancy by inducing stemness properties and EMT in ESCC." (PMID 36553636, 2022). "NANOG also works together with other stemness factors, such as MYC, OCT4, KLF4, SOX2, SOCS2, or ALDH1A1, to control a set of target genes that have important functions in embryonic stem cells and, plausibly, in tumor cells." (PMID 35104240, 2022). "Recent study showed TGF-β and H19 axis via Sox2 importantly regulates hepatocarcinogenesis, regardless its lower expression level in HCC tumor tissue." (PMID 36578923, 2022). "Subsequently, it was revealed that FOXQ1 knockdown led to inhibition of tumor sphere growth as well as down-regulated expression of stemness markers (CD133, SOX2 and OCT4) in HCT116R cells, whereas FOXQ1 overexpression led to the opposite in HT29R cells." (PMID 35183223, 2022). "A different study showed the importance of the embryonic stem cell factor Sox2 for ALCL xenograft growth, a hint towards the importance of progenitor cells for tumor propagation." (PMID 35646639, 2022). "To further analyze the correlation between expression of cell markers (SOX2, SOX9, Nestin, and Ki67) and the proximity to the SVZ, we used the distance from centroid of tumor to SVZ." (PMID 35795469, 2022). "We further identify a SOX2:miR-10b-5p:TET2 axis that represses TET2 expression, represses 5hmC, increases 5mC levels, and induces GBM cell stemness and tumor-propagating potential." (PMID 35136034, 2022). "Although cytotoxic chemotherapy eradicates most tumor cells, CSCs are more protected and capable to recapture the heterogenic tumor mass through self-renewal with high expression of aldehyde dehydrogenase 1 A (Aldh1A), CD133, CD44 and Sox2." (PMID 35804016, 2022). "Tumor tissue were collected, and OCT4, SOX2, and NANOG expressions were assessed by immunohistochemistry (IHC) staining to investigate the association of stemness markers with overall survival (OS)." (PMID 36085021, 2022). "Consistent with our expectations, we observed high expression of SOX2 and ALDH1A1 in CxSCC tumor buds." (PMID 35860042, 2022). "The expression of Lin28 targeted SOX2, and HMGA2 oncogenes were also suppressed by these inhibitors, supporting that these compounds can block the pluripotency of tumor cells and suppress treatment-resistant tumor progression." (PMID 36428779, 2022). "We quantified the number of tumor stem cells in CNE-1 using soft agar colony assay and SOX2, CD44 protein expression levels were determined by western blot analysis." (PMID 36403050, 2022). "Generally, CSCs have surface markers that differ from those of tumor cells, such as Nanog, CD44, SOX2, and OCT4." (PMID 36245214, 2022). "SOX2, KLF4, NANOG, and OCT4 are notorious for their specific expression in CSCs of HNSCC, which promoted stemness and tumor progression and lead to poor prognosis." (PMID 36451812, 2022). "Immunostaining was performed to assess both proliferative/stem cell (Nestin, Sox2, Ki67, Vimentin, SSEA1, CD133) and quiescent (Cd9 and Gfap) markers within the tumours." (PMID 36420140, 2022).